SOX2 (SRY-box transcription factor 2)
Diseases named in the same sentence as SOX2 in open-access papers (continued):
Sharing a sentence is not in itself a finding about the gene and the disease.
pilocytic astrocytoma (2 papers, 2011 to 2023). Pilocytic astrocytoma is a rare subtype of low-grade glioma of the central nervous system characterized by a well circumscribed, often cystic, brain tumor with a discrete mural nodule and long, hair-like projections that extend from the neoplastic astrocytes. "In pilocytic astrocytomas (Grade I) Sox2 could only be detected in less than 20% of the cells." (PMID 21483788, 2011).
prostatic intraepithelial neoplasia (2 papers, 2016 to 2025). "However, in high-grade prostatic intraepithelial neoplasia, SOX2 shows mixed staining in both basal and luminal cells." (PMID 40821114, 2025).
salivary gland tumors (2 papers, 2011 to 2025). "We found that salivary gland tumors induced by Plag1 overexpression contained CD44hi cells that incorporated BrdU at a low cycle rate and retained BrdU better than CD44neg cells; and that CD44hi cells have higher levels of transcripts of stem cell related genes, Oct-4, Nanog, Sox2 and telomerase." (PMID 21858056, 2011).
squamous intraepithelial lesions (2 papers, 2020 to 2022). "SOX2 negative (areas in) high-grade squamous intraepithelial lesions (HSIL) have been reported before, while also downregulation of SOX2 was seen during the initial stages of the invasive process." (PMID 35945296, 2022).
thyroid (2 papers, 2021 to 2023). "SOX2 has been reported also as an ATC stemness marker and as strongly involved in thyroid CSC-dependent chemoresistance." (PMID 37393309, 2023).
Tracheoesophageal fistula (2 papers, 2020 to 2024). An abnormal connection (fistula) between the esophagus and the trachea. "In contrast, patients with tracheoesophageal fistulas exhibited a noticeable shift, with SOX2 displaying clear nuclear labeling in epithelial cells." (PMID 38355689, 2024). "Contributions of SOX2 to esophageal specification of AFG epithelia have been demonstrated using combinations of hypomorphic Sox2 alleles, leading to degrees of tracheoesophageal fistula, similar to various aspects of human congenital tracheoesophageal fistula cases." (PMID 31988094, 2020).
vascular tumor (2 papers, 2015 to 2021). "IHC staining for the stem cell reprogramming factors Oct4, Nanog, Myc, Klf4, and Sox2 was performed in the vascular tumor samples as well as the two control tissue sets." (PMID 26412983, 2015). "Thus, in this study we used immunohistochemical analysis to examine the expression of the stem cell reprogramming factors Oct4, Sox2, Nanog, Myc, and Klf4 in 71 diverse benign and malignant vascular tumors." (PMID 26412983, 2015). "Interestingly, the enhanced levels of Oct4, Nanog, Myc, and Sox2 protein were approximately equivalent between benign, borderline, and malignant vascular tumors." (PMID 26412983, 2015). "Semi-quantitative evaluation of our immunohistochemical staining revealed that protein expression of Oct4, Nanog, Myc, and Sox2, but not Klf4, was significantly increased in benign, borderline, and malignant vascular tumors relative to non-diseased vascular tissue controls." (PMID 26412983, 2015).
vulva cancer (2 papers, 2020 to 2024). A primary or metastatic malignant neoplasm involving the vulva. "Of the 14 cases that progressed to vulvar cancer within two years, 12 (86%) and 7 (50%) were found to be CK17 and SOX2 positive, respectively." (PMID 39682153, 2024). "There is a potential link between Sox2 amplification/over-expression and HPV-positivity in vulva cancer, which could also apply to the explanation of exclusive Sox2-p63 activation in CC." (PMID 33194730, 2020). "A significant correlation between CK17 and SOX2 staining and progression to vulvar cancer within two years could not be demonstrated (p = 0.713 and p = 0.096, respectively)." (PMID 39682153, 2024).
vulvar carcinoma (2 papers, 2020 to 2021). "HPV infection drives switches in SOX2 expression in the transformation zone in the uterine cervix, and SOX2 locus amplification was associated with HPV ISH positivity in vulvar carcinoma." (PMID 33182283, 2020). "Interestingly, HPV infection drives switches in SOX2 expression in the transformation zone in the uterine cervix, and SOX2 locus amplification was related with HPV mRNA positivity in vulvar carcinoma." (PMID 33789601, 2021).
Zinc deficiency (2 papers, 2019 to 2020). A deficiency of the essential metal Zinc; an essential cofactor for many enzymes. "We demonstrated that a zinc deficiency significantly increased the number of apoptotic hiPSC-CMs and the expression level of Sox2 and Oct4 protein, while decreasing the protein expression levels of cTnT in hiPSC-CMs." (PMID 33211757, 2020). "Maternal marginal zinc deficiency caused a 95% decrease in E14 cortical Sox2 levels compared to controls." (PMID 30890920, 2019). "Similarly, zinc deficiency caused the differentiation index proteins, Sox2 and Oct4, to increase and the expression level of cTnT to decrease." (PMID 33211757, 2020). "Thus, not only ERK1/2 but also Sox2 and Pax6 downregulation at a period of active progenitor proliferation can contribute to the decrease in the number of fetal brain NPCs as a consequence of maternal marginal zinc deficiency." (PMID 30890920, 2019).
acromegaly (1 paper, 2020). Acromegaly is an acquired disorder related to excessive production of growth hormone (GH) and characterized by progressive somatic disfigurement (mainly involving the face and extremities) and systemic manifestations. "Similar to the impact of the excess GH on abcg2a gene expression in the kidney, the RNA-seq data revealed a significant reduction in the expression of abcg2a in various organs, as well as Sox2 (a neural stem cell marker) in the brain of the acromegaly zebrafish." (PMID 32517323, 2020).
actinic keratosis (1 paper, 2026). A precancerous lesion of the skin composed of atypical keratinocytes. "We observed that SOX2 levels were increased in 27% of premalignant actinic keratosis (AK) and 35% of cSCC lesions, whereas SOX2 expression levels were low in normal skin (NS)." (PMID 41507151, 2026).
Adamantinomatous Craniopharyngioma (1 paper, 2017). A craniopharyngioma consisting of broad strands, cords and bridges of a multistratified squamous epithelium with peripheral palisading of nuclei. "Expression of oncogenic β-catenin in Sox2+ young adult pituitary stem cells leads to formation of clusters of stem cells and induction of tumours resembling human adamantinomatous craniopharyngioma (ACP), derived from Sox2− cells in a paracrine manner." (PMID 29180744, 2017).
adenocarcinoma in situ (1 paper, 2020). A lesion in which the normally situated glands are partially or completely replaced by atypical cells with malignant characteristics. "When studying the topographical distribution of these two markers in squamous and glandular preneoplastic lesions (SIL and adenocarcinoma in situ; AIS), we noted an almost exclusive expression of SOX2 in SIL and a more complex, combined SOX2 and SOX17 expression pattern in AIS." (PMID 32644288, 2020).
adrenocortical adenoma (1 paper, 2022). "However, immunohistochemistry confirmed that the stemness markers SOX2, CD44, and OCT4 were highly expressed in MCMT with greater adrenocortical adenoma density than in PCC." (PMID 36187098, 2022).
airway allergy (1 paper, 2024). "Expression of SOX2+ ORN progenitors were affected in the nasal mucosa due to RSV transient infection.Delayed RSV clearance and exacerbated progenitors damage observed in airway allergy mice." (PMID 38543591, 2024).
allergic asthma (1 paper, 2021). A asthma with a basis in a pathological type I hypersensitivity reaction. "Specifically, Club cells were reported to play a major role in allergic asthma and SOX2 was reported to be required for goblet cell differentiation after allergen sensitization." (PMID 33942458, 2021).
Alpers syndrome (1 paper, 2024). A cerebral degeneration that results in progressive degeneration of grey matter in the cerebrum and has_symptom convulsions. "Additionally, the overexpression of SOX2-positive neural progenitors and an increased number of GFAP-positive astrocytes point towards astrogliosis in the context of cortical neuronal loss, a hallmark of brain pathology in Alpers' syndrome." (PMID 38385069, 2024).
anal squamous cell carcinoma (1 paper, 2023). A squamous cell carcinoma (SCC) arising from the anal canal or the anal margin (perianal skin).
anaplastic astrocytoma (1 paper, 2025). "SOX2 mutations were present in 1.52% of anaplastic astrocytomas, 0.54% of GBMs, and 0.076% of diffuse gliomas." (PMID 40679044, 2025).
Astigmatism (1 paper, 2020). A type of refraction error associated with abnormal curvatures on the anterior and/or posterior surface of the cornea. "Similarly, the Open Targets SNP and gene co-localisation results point to sharing of signals with astigmatism-related traits (CRYAA, SOX2 and GLTSCR1 loci), cardio-metabolic traits, anthropometric and blood cell traits." (PMID 33311586, 2020).
bone metastasis (1 paper, 2025). Transfer of a neoplasm from its primary site to bones. "Exosomes extracted from peripheral blood of NSCLC patients with bone metastasis exhibit a significant upregulation of SOX2 overlapping transcript (SOX2-OT), which is closely associated with lower overall survival rates." (PMID 40176898, 2025).
Bosch-Boonstra-Schaaf optic atrophy syndrome (1 paper, 2025). Optic atrophy-intellectual disability syndrome is a rare, hereditary, syndromic intellectual disability characterized by developmental delay, intellectual disability, and significant visual impairment due to optic nerve atrophy, optic nerve hypoplasia or cerebral visual impairment. "NR2F1 mutations are responsible for the Bosch-Boonstra-Schaaf optic atrophy syndrome (OMIM #615722; BBSOAS), whereas SOX2 mutations cause micro- or anophtalmia (OMIM #206900, Microphtalmia, syndromic 3; optic nerve hypoplasia and abnormalities of the central nervous system)." (PMID 40631402, 2025).
brain arteriovenous malformations (1 paper, 2020). "ECs within brain arteriovenous malformations in mice undergo SOX2, and JMJD5-mediated EndMT that can be suppressed using Pronethalol hydrochloride." (PMID 32226439, 2020).
brain glioma (1 paper, 2019). A malignant glioma that involves the brain. "SOX2 high expression is common in brain gliomas, a tendency of decreased SOX2 expression in recurrent HGG was evidenced." (PMID 31718604, 2019).
cerebellar degeneration (1 paper, 2019). Degeneration of the cerebellum. "SOX2 antibodies were detectable in 61% of patients with LEMS-SCLC, and in other paraneoplastic disorders, such as opsoclonus-myoclonus and paraneoplastic cerebellar degeneration, only when there was an underlying SCLC." (PMID 30445363, 2019).
cerebral tumour (1 paper, 2017). "Our results point to the conclusion that Sox2 and Sox9, seem to play essential roles not only in the specific formation of aCP, but also in processes involving the cerebral tumour environment, which needs to be illuminated in the future." (PMID 29158570, 2017).
Cerebral visual impairment (1 paper, 2022). A form of loss of vision caused by damage to the visual cortex rather than a defect in the eye. "It will be interesting in the future to search for mutations in SOX2, SOX2 regulatory elements, or SOX2 target genes in patients with cerebral visual impairment." (PMID 35626641, 2022). "In fact, Sox2 ablation in the visual thalamus in mouse resulted in problems with the differentiation of the visual system, defects found in humans with cerebral visual impairment." (PMID 35626641, 2022).
cerebrovascular disease (1 paper, 2023). "miRNA 145 is established to suppress stem cell pluripotency markers, such as OCT4, SOX2, and NANOG, and increases levels of SMA in SMCs; thus, disruption of this miRNA likely causes MMD-like cerebrovascular disease through a similar mechanism to ACTA2 p.R179 variants." (PMID 37886459, 2023).
cervical tumors (1 paper, 2015). "This study examined the clinical correlation and prognostic significance of stemness-related OCT4 and SOX2 protein expression assessed by IHC in premalignant and malignant cervical tumors." (PMID 26706028, 2015). "The results demonstrate that OCT4 and SOX2 protein expression is elevated in premalignant and malignant cervical tumors compared to normal cervix and this finding is consistent with a previous study." (PMID 26706028, 2015). "OCT4 and SOX2 showed high expression in premalignant and malignant cervical tumors." (PMID 26706028, 2015). "Notably, OCT4 and SOX2 were significantly co-expressed in premalignant cervical lesions, but not in malignant cervical tumor." (PMID 26706028, 2015).
Chlamydia infection (1 paper, 2024). "Utilizing biochemical methods and imaging, our study discloses that acute Chlamydia infection in human MSCs leads to the downregulation of transcription factors Oct4, Sox2, and Nanog, suggesting a loss of pluripotency markers." (PMID 39467689, 2024).
Chorioretinal coloboma (1 paper, 2010). Absence of a region of the retina, retinal pigment epithelium, and choroid. "Recent data has identified a missense mutation in SOX2 in an extended pedigree with phenotypes as varied as A/M, isolated iris hypoplasia, iris and chorioretinal coloboma, pupil defects, and hypermetropia, suggesting a broader phenotypic spectrum associated with SOX2 mutations." (PMID 20454695, 2010).
clear cell adenocarcinoma (1 paper, 2010). A malignant neoplasm composed of glandular epithelial clear cells. "It is interesting to note that, among all clinicopathological parameters examined, hypermethylation of SOX2 promoter was linked marginally to histologic subtypes, being relatively more common in type II serous and clear cell adenocarcinomas." (PMID 20814443, 2010). "Hypermethylation of SOX2 tended to be more frequently found in type II serous or clear cell adenocarcinoma." (PMID 20814443, 2010).
Co-infection (1 paper, 2012). "Co-infection of utricles with adenoviral vectors separately encoding Oct3/4, Klf4, Sox2, and the degradation-resistant T58A mutant of c-Myc (c-MycT58A) triggered significant levels of supporting cell S-phase entry as assessed by continuous BrdU labeling." (PMID 23119091, 2012).
colorectal adenoma (1 paper, 2019). An adenoma that arises from the colon or rectum. "There is limited data on the expression of target genes of the miR-200 family in colorectal adenoma and, to the best of our knowledge, only CDKN1B and SOX2 have so far been investigated, excluding studies on dysplastic lesions in inflammatory bowel diseases." (PMID 31623346, 2019).
craniorachischisis (1 paper, 2014). Craniorachischisis is the most severe form of neural tube defect in which both the brain and spinal cord remain open to varying degrees. "Indeed, the aortic arch abnormalities that are highly penetrant in Lp/Lp and in the Vangl2flox/flox; Sox2-Cre and Vangl2flox/flox; PGK-Cre mutants described here, may be secondary to these gross abnormalities in body form, as they are only observed in the presence of craniorachischisis." (PMID 25521757, 2014).
cystic tumor (1 paper, 2020). "Although the immunohistochemical expression of only two markers is insufficient to prove that OKC is a cystic tumor, our results suggest that SOX2 and BCL-2 are related to the persistent growth potential of OKC, a characteristic compatible with its neoplastic nature." (PMID 31967981, 2020).
delirium (1 paper, 2022). A disorder characterized by confusion; inattentiveness; disorientation; illusions; hallucinations; agitation; and in some instances autonomic nervous system overactivity. "We did not observe any difference in the marker of stemness (Sox2 or Nestin), when comparing the two groups (delirium vs non-delirium) and the two time points." (PMID 36195636, 2022).
demyelinating CNS diseases (1 paper, 2015). "Targeting p75NTR/Sox2-expressing Schwann cells to enhance their differentiation into competent remyelinating cells appears to be a promising therapeutic approach for inflammatory/demyelinating CNS diseases." (PMID 26196511, 2015).
demyelinating disease (1 paper, 2015). A broad group of disorders that affect the myelin sheaths that cover the neurons. "In addition to the endogenous role of Sox2 in the non-pathologic state, populations of Sox2-immunopositive cells have been detected near sites of injury in the CNS in mice including lesions of demyelinating disease, hypoglossal nerve avulsion, and penetrating stab wounds." (PMID 25713758, 2015).
diabetic retinopathy (1 paper, 2025). "We aimed to explore the regulatory effects of methyltransferase-like 3 (METTL3) on diabetic retinopathy (DR) by regulating the m6A modification of SOX2 mRNA and elucidating the underlying molecular mechanism." (PMID 40727611, 2025).
disc degeneration (1 paper, 2020). "In a second phase, between day 7 and day 14, IVD cells combined with DWJM showed a down-regulation of SOX2 and SOX9 together with an up-regulation of TRPS1, a chondrogenic transcription factor previously identified by us as chondroprotective and associated with the lower grade of disc degeneration." (PMID 32292779, 2020).
endometrial tumors (1 paper, 2018). "We further identified the presence of genomic amplifications in SOX2 and MYC in endometrial tumors, and we observed the association of SOX2 and MYC amplifications with poor differentiation status." (PMID 30510261, 2018). "A correlation analysis showed that both SOX2 and MYC amplifications were significantly associated with advanced grade in endometrial tumors." (PMID 30510261, 2018). "We observed that SOX2 expression correlates with lymph node infiltration of endometrial tumors." (PMID 30510261, 2018). "Here, we observed that SOX2 level correlates with EGFR expression in late-stage endometrial tumors and cancer cells, in which SOX2 expression promotes EGFR, forming a SOX2–EGFR feedback." (PMID 30510261, 2018). "In this study, we observed that the expression of SOX2 and MYC, but not that of OCT4 and NANOG, in endometrial tumors is associated with poor histological differentiation and prognosis, suggesting the involvement of SOX2 in oncogenesis." (PMID 30510261, 2018). "Thus, in this study, we checked the association of SOX2, OCT4, NANOG, and MYC expressions with histological differentiation of endometrial tumors, and observed that the expressions of SOX2 and MYC, but not that of OCT4 and NANOG, correlate with advanced tumor grades." (PMID 30510261, 2018).
esophageal tumors (1 paper, 2023). "Moreover, in the induced esophageal tumors of Otud6b cKO mice, the expression of β‐TrCP and the differentiation marker CK13 was decreased, and the levels of SOX2 and NANOG were increased." (PMID 37038094, 2023).
esophagitis (1 paper, 2022). An acute or chronic inflammatory disease affecting the esophageal wall.
Fanconi anaemia (1 paper, 2017). "Mutations in PTEN, SOX2 and NOTCH1, which are also frequently associated with SCLC, and BRCA1/2 or other known Fanconi anaemia genes were also not detected." (PMID 29387807, 2017).